LINC02873 (long independently transcribed non-coding RNA 2873)
Synonyms: FLJ39058; C11orf44
Gene: Long non-coding RNA gene on chromosome 11 (130,631,289 to 130,717,352, forward strand). Ensembl gene ENSG00000175728.
Diseases named in the same sentence as LINC02873 in open-access papers:
LINC02873 is named in the same sentence as 1 disease in open-access papers, as found by Europe PMC text mining. Sharing a sentence is not in itself a finding about the gene and the disease.
LINC02873 shares sentences with these, for which no sentence is quoted: tumor (1 paper).